TNF (tumor necrosis factor)
Diseases named in the same sentence as TNF in open-access papers (continued):
Sharing a sentence is not in itself a finding about the gene and the disease.
head and neck squamous cell carcinoma (34 papers, 2000 to 2025). A squamous cell carcinoma that arises from any of the following anatomic sites: lip and oral cavity, nasal cavity, paranasal sinuses, pharynx, larynx, and salivary glands. "For instance, TNF-α is associated with higher rates of metastasis and facilitates angiogenesis in head and neck squamous cell carcinoma (HNSCC) patients by enhancing the expression of vascular growth factors and increasing the activation of the ERK3 pathway." (PMID 41007256, 2025). "Immune and radiation resistance of cancer cells to cytotoxicity mediated by TNFα is promoted by the transcription factor NF-κB in several cancers, including head and neck squamous cell carcinoma (HNSCC)." (PMID 39392349, 2024). "For example, USP14 has enhanced expression in head and neck squamous cell carcinomas and promotes TNF-α-inducible NF-κB activity." (PMID 37917013, 2023). "TNFα is a key mediator of immune, chemotherapy and radiotherapy-induced cytotoxicity, but several cancers, including head and neck squamous cell carcinomas (HNSCC), display resistance to TNFα due to activation of the canonical NFκB pro-survival pathway." (PMID 37055579, 2023). "It was reported to block TNFα-induced IL-8 secretion to inhibit head and neck squamous cell carcinoma progression and enhance sensitivity to TNFα-induced cell death." (PMID 34112144, 2021). "An association between USP4 and RIP1 was reported to impair NF-κB activation and exacerbate TNF-α–induced apoptosis in head and neck squamous cell carcinoma (HNSCC)." (PMID 33681193, 2021). "Additionally, USP14 inhibits the degradation of IκBα, thereby suppressing NFκB signalling and enhancing sensitivity to TNFα‐induced cell death in head and neck squamous cell carcinoma, offering a potential strategy to overcome TNFα resistance in these cancers." (PMID 40988122, 2025). "Similarly, TNF-α can inhibit Snai2 ubiquitination in head and neck squamous cell carcinoma by suppressing the NF-κB signaling pathway, promoting EMT and metastasis." (PMID 39062049, 2024). "Moreover, SPP1+ macrophages augment the secretion of TNF-α and IL-1β via the NF-κB pathway, further supporting proliferation in head and neck squamous cell carcinoma (HNSCC)." (PMID 41417432, 2025). "Human TIML NK cells exhibit an enhanced secretion of IFN-γ and TNF, alongside both immediate and sustained cytotoxic activity against head and neck squamous cell carcinoma (HNSCC) cell lines and primary tumor targets, surpassing the functional capacity of conventional NK cells." (PMID 40498022, 2025). "In a preclinical model of head and neck squamous cell carcinoma (HNSCC), MUC1-CAR-T cells specifically killed MUC1+ HNSCC cell lines in vitro and secreted IL-2, interferon γ (IFN-γ), and TNF-α." (PMID 38727261, 2024). "In head and neck squamous cell carcinoma, ALDH+ cells inhibit T-cell proliferation and secrete cytokines, such as interferon γ (IFN-γ), IL-2, and tumor necrosis factor-α (TNF-α), promoting tumorigenesis and drug resistance." (PMID 39456967, 2024). "Our bioinformatics analysis revealed significant overexpression of TNF and TNFR2 in head and neck squamous cell carcinoma." (PMID 38412319, 2024). "Head and neck squamous cell carcinoma (HNSCC) remains a prevalent diagnosis with current treatment options that include radiotherapy and immune-mediated therapies, in which tumor necrosis factor-α (TNFα) is a key mediator of cytotoxicity." (PMID 36831373, 2023). "EMT observed in head and neck squamous cell carcinoma (HNSCC) was shown to be induced by an inflammatory microenvironment, specifically the secretion of TNFα which activates the NF-κB pathway." (PMID 37853467, 2023). "Furthermore, in human head and neck squamous cell carcinoma (HNSCC) cell lines, cREL and ΔNp63 form a complex in response to the inflammatory cytokine TNFα to activate NF-κB and AP-1 pathways." (PMID 37638000, 2023).
head and neck squamous cell carcinoma (continued). "RT can also upregulated CCL2 chemokine in tumor cells, leading to a CCR2-dependent accumulation of tumor necrosis factor alpha (TNFα)-producing monocytes and CCR2+ regulatory T cells (Treg) in a murine model of head and neck squamous cell carcinoma." (PMID 34094967, 2021). "ALDH1-positive head and neck squamous cell carcinoma cells inhibited T-cell proliferation more efficiently than ALDH1-negative cells, and inhibited cytokine, interferon γ (IFN-γ), Interleukin-2 (IL-2) and tumor necrosis factor α (TNF-α)." (PMID 36497050, 2022). "However, TNF-α has been detected in tumour and serum of patients with head and neck squamous cell carcinoma (HNSCC), and tumour cell lines derived from this environment often exhibit resistance to TNF-α-induced cell death." (PMID 11044363, 2000). "In a head and neck squamous cell carcinoma (HNSCC) murine model, researchers found that RT could upregulate CCL2 production and induce the CCR2-dependent accumulation of Tregs and TNF α-producing monocytes and macrophages, thereby playing an immunosuppressive role." (PMID 33789758, 2021). "In addition, USP4 plays a tumor suppressor role in head and neck squamous cell carcinoma (HNSCC) by negatively regulating RIP1-mediated NF-κB activation and promoting TNF-α-induced apoptosis." (PMID 30335615, 2018).
idiopathic pulmonary fibrosis (34 papers, 2006 to 2026). Idiopathic pulmonary fibrosis (IPF) is a nonneoplastic pulmonary disease that is characterized by the formation of scar tissue within the lungs in the absence of any known cause. "Various agents have previously been reported to cause such pulmonary side effects as fibrosing alveolitis (e.g. bleomycin, busulfan, or trastuzumab) or granulomatous lung disease (e.g. methotrexate, BCG, TNF-α blocking agents, gefitinib, or everolimus)." (PMID 23691384, 2013). "Idiopathic pulmonary fibrosis (IPF) is a lethal chronic progressive pulmonary disease and the TNF-alpha transgenic mouse is an animal model for human IPF." (PMID 32708322, 2020). "Idiopathic pulmonary fibrosis (IPF) fibroblasts secrete TNF-α, which alters the behavior of neighboring normal fibroblasts—promoting NFκB pathway activation—suggesting a self-perpetuating, fibroblast-driven mechanism in IPF pathology." (PMID 40806851, 2025). "In patients with idiopathic pulmonary fibrosis (IPF), TRAF2 overexpression is correlated with elevated TNF-α levels." (PMID 40438045, 2025). "The TNF-Tg mice also exhibit a specific phenotype of ILD, nonspecific interstitial pneumonia (NSIP, inflammatory and fibrotic), more prevalent clinically in females relative to usual interstitial pneumonia (UIP, predominately fibrotic), which has a predilection to affect males." (PMID 36732826, 2023).
prion disease (34 papers, 2012 to 2025). A transmissible disease that is caused by a protein that is able to induce abnormal folding of normal cellular proteins, leading to characteristic spongiform brain changes, which are associated with neuronal loss without an inflammatory response. "Hartmann and colleagues showed that the abolishment of C3+ astrocytes in mice deficient in TNFα, interleukin‐1α and complement component C1qa coincided with accelerated CNS prion disease." (PMID 35852018, 2022). "This dysregulation of TACE renders diseased neurons highly sensitive to TNFα-associated inflammation and amplifies the production of PrPSc in prion diseases and Aβ peptides in AD but also in prion diseases." (PMID 35840975, 2022). "Whereas CNS prion disease was unaltered in mice deficient in TNF-α or C1q, the combined deficiency in TNF-α, IL-1α and C1q was shown to accelerate the disease." (PMID 33023255, 2020). "The upregulation of pro-inflammatory cytokines like IL-1-β and TNF-α occurs as prion diseases progress." (PMID 40498027, 2025). "The present study meticulously examines the role of TNFR1, TNFα and their adaptor proteins within prion disease pathology, elucidating their molecular dynamics and possible functional implications." (PMID 38802941, 2024). "This protective role for microglial C1qa and TNFα in prion disease in the CNS contrasts with the facilitative role observed for C1qa, C3, and TNFα in peripheral prion pathogenesis." (PMID 38786054, 2024). "TNFα is the most widely studied DR ligand in various neurodegenerative diseases, including prion diseases." (PMID 38802941, 2024). "Unexpectedly, elimination of three microglia-derived factors TNF-α, IL-1α and C1qa, which were thought to drive polarization of astrocytes into a neurotoxic state, accelerated the progression of prion diseases." (PMID 33980286, 2021). "Of note, TNF-α, IL-1α and C1qa are upregulated in mouse models of prion disease and TNF-α and IL-1α in human CJD, which would make polarization of astrocytes towards A1 very likely in prion diseases." (PMID 31118110, 2019). "Surprisingly, abolishment of C3+-astrocyte formation by knocking out TNF-α, IL-1α and C1qa accelerated the prion disease course." (PMID 31118110, 2019). "Although the deposition of misfolded PrPSc was unchanged, we found that knockout of TNF-α, IL-1α and C1qa with the abolishment of C3+-astrocyte formation let to a significant acceleration of the prion disease course." (PMID 31118110, 2019). "We then investigated the impact of these astrocytes on prion disease pathophysiology by prion infecting mice with a knockout of the three cytokines TNF-α, IL-1α and C1qa, which are unable to develop A1-astrocytes upon stimulation." (PMID 31118110, 2019). "In order to evaluate the activation state of microglia at onset and end-stage prion disease in wild-type and Neil3 Ko mice we compared expression levels of microglial markers Cd68, Cd86 and inflammation markers TNFα and Il1ß at both time-points." (PMID 27886261, 2016). "However, there are many open questions since the removal of TNF-α, IL-1α, and C1qa had a minimal impact on suppressing A1-specific markers in prion-infected animals, which unexpectedly hastened the progression of prion diseases." (PMID 38790392, 2024). "However, contrary to expectations, triple TNFα−/−IL1α−/−C1q−/− knockout accelerated the progression of prion diseases, questioning the role of microglia-secreted TNFα, IL1α, and C1q as universal drivers of the neurotoxic astrocytes." (PMID 38900746, 2024). "The pro-inflammatory cytokine TNF-α is also central in the pathogenesis of prion diseases." (PMID 38790392, 2024). "The effects of systemic LPS treatment on CNS prion disease coincide with the enhanced abundance and inflammatory activation of the microglia, as well as elevated production of the pro-inflammatory cytokines TNF-α, IL-1β and IL-6, and cytotoxic mediators such as nitric oxide." (PMID 33023255, 2020).
prion disease (continued). "Conversely, TNF-α, IL-4, IL-6, IL-12(p40), IL-12(p35), IL-13, and transforming growth factor-β1 are probably not pathogenic in prion disease because knockout of these cytokines did not change the disease course of prion-inoculated mice." (PMID 24219883, 2013). "Therefore, it would be interesting to determine, if C3aR is altered in prion diseases and could pose a more suitable target than the cytokine triad TNF-α, IL-1α and C1qa." (PMID 31118110, 2019). "Lastly, ten terms from the KEGG database were enriched including ALS, AD, MAPK signalling, apoptosis, TNF signalling, NF-kappa-B signalling, IL-17 signalling, RIG-I-like receptor signalling, VEGF signalling, and Prion disease." (PMID 33964983, 2021). "These pathways included the Toll-like receptor, mTOR, AMPK, FoxO, B cell receptor, Jak-STAT, cAMP, Apoptosis, T cell receptor, TNF, Chemokine, PPAR, MAPK, Notch, PI3K-Akt, ErbB, Rap1, cGMP-PKG, VEGF, Calcium, Wnt, NF-κB, Ras, Hippo, Prion diseases, and Fc epsilon RI signaling pathway." (PMID 38183097, 2024). "Several studies have suggested that the up-regulation of TNFα, IL1β, IL6, and COX2 plays important roles in many inflammatory diseases including cytotoxicity in brain injuries and many neurodegenerative diseases such as AD, PD, and prion diseases." (PMID 32560481, 2020). "This suggests that in the steady state, factors independent of microglial-derived TNF-α, IL-1α and C1q are required for the activation of astrocytes in the prion disease-affected brain." (PMID 33023255, 2020). "To investigate their impact on prion disease pathophysiology and to evaluate their potential therapeutic targeting, we infected TNF-α, IL-1α, and C1qa Triple-KO mice (TKO-mice), which do not transit astrocytes into A1, with prions." (PMID 31118110, 2019). "TNF-α was significantly upregulated upon terminal prion disease in brains of WT animals, but as expected, not abundant in the TKO-mice." (PMID 31118110, 2019). "Knockout or depletion of either TNF-α or C1qa in mouse models of prion disease did not influence prion disease course after intracerebral prion infection, however, microglia homeostatic phenotypes had not been determined in these studies." (PMID 31118110, 2019). "However, independent studies have shown that deficiency in complement component C3 does not affect the development of CNS prion disease, and TNFα was undetectable in the brains of prion‐infected Csf1rΔFIRE mice." (PMID 35852018, 2022). "Thus, it is plausible that the systemic production of high levels of pro-inflammatory mediators such as TNF-α and IFN-γ in response to infection with the SARS-Cov-2 virus could accelerate the neurodegeneration in patients with concurrent prion disease or other neurodegenerative disorders." (PMID 33023255, 2020). "Therefore, we intra-cerebrally infected Triple-KO mice (TKO) lacking expression of TNF-α, IL-1α and C1qa (which fail to develop A1 reactive astrocytes following inflammatory insult) with RML-prions and determined pathophysiology of prion disease progression in comparison to infected WT-mice (WT)." (PMID 31118110, 2019).
renal dysfunction (34 papers, 2009 to 2025). "Hypotension, followed by coagulopathy and renal dysfunction, is strongly associated with the increase of TNF-α." (PMID 23737912, 2013). "We provided the first evidence that GDF-15 may be a novel biomarker for identifying high-risk patients with muscle wasting and renal dysfunction, compared with tumor necrosis factor α (TNFα) or insulin growth factor-1 (IGF-1) in cardiovascular surgery patients." (PMID 31581569, 2019). "PQ exposure raises pro-inflammatory cytokines like Tumor necrosis factor alpha (TNF-α) and Interleukin 6 (IL-6), which further mediate inflammation and renal dysfunction." (PMID 41509108, 2025). "Renal dysfunction has been proven to increase the cytokines level in our body, including interleukin -1, IL-6, and tumor necrosis factor-α." (PMID 37041544, 2023). "Among the 71 patients in the TNF-i group, in addition to 3 patients with liver dysfunction and 1 with renal dysfunction, 4 patients with DAS remission at baseline were excluded; thus, 63 patients were included in this analysis." (PMID 28800780, 2017). "Among the abundant cytokines, TNFα and IL-1β play more important roles in inflammation-mediated renal dysfunctions." (PMID 28367225, 2017). "Although both drugs reduced NO synthesis and TNF-α gene overexpression, only AG improved renal dysfunction and liver damage and reduced liver oxidative stress." (PMID 26692194, 2015). "The growth and decay of serum creatinine, which is elevated during renal dysfunction, occurred on a time scale that parallels Group A [TNF-α, IL1, and IL10] response." (PMID 23049677, 2012). "Similarly, renal dysfunction increases plasma levels of pro-inflammatory cytokines, including interleukin-6, tumor necrosis factor-α, and monocyte chemotactic protein-1, promoting vascular inflammation." (PMID 40129657, 2025). "These cases indicate that biologic treatments like secukinumab and TNF inhibitors may offer potential therapeutic options for HS patients with renal dysfunction." (PMID 39898256, 2025). "Moreover, a strong correlation was evident between the expressions of TLR-4, TLR-2, NF-κB, and TNF-α genes and hepato-renal dysfunction indicators." (PMID 37045926, 2023). "Notably, in cirrhotic ascitic rats from our study, chronic pioglitazone pre-treatment attenuated LPS-induced TNFα/NFκB-mediated acute on chronic renal dysfunction by suppressing renal IL-6, ICAM-1 and VCAM-1." (PMID 34831270, 2021). "TNF-α may be a direct inducer of hypotension, coagulopathy and renal dysfunction." (PMID 23737912, 2013). "A clinical study further corroborates these findings, showing that AKI patients exhibit elevated serum levels of cf-DNA and MPO-DNA, which correlate with renal dysfunction (elevated Scr and BUN) and pro-inflammatory cytokines IL-1β and TNF-α release." (PMID 41244813, 2025). "Linear regression analysis revealed a good correlation of serum IL-21 (ρ = −0.018, P = 0.016) and TNF-α (ρ = 0.006, P < 0.001) levels with serum creatinine (Cr), indicating that circulating cytokines could be a potential biomarker for monitoring renal dysfunction." (PMID 32991326, 2020). "In cirrhotic patients with spontaneous bacterial peritonitis (SBP), those with renal impairment had significantly higher plasma and ascitic fluid TNFα levels than those without renal dysfunction." (PMID 34831270, 2021). "Abundant adipocytes could produce a large number of tumor necrosis factor receptor (TNF-α), which neutralized the cardiotoxicity of TNF-α, thus counteracting the negative effects of renal dysfunction." (PMID 36969848, 2023). "However, side effects, such as nausea, vomiting, flatulence and abdominal pain, high cost, resistance, and the hepatotoxicity of anti-TNFα antibody limit the application of agents with anti-TNF effects in advanced cirrhotic patients with circulatory and renal dysfunction." (PMID 33513830, 2021).
renal dysfunction (continued). "We demonstrated that urine osmotic pressure, urine specific gravity, I-FABP, IFN-γ, IL-1β, and TNF-α were reduced by 8 weeks of IMP supplementation, indicating that IMP may have potential in preventing strenuous exercise-induced renal dysfunction, increased intestinal permeability, and inflammation." (PMID 32143279, 2020).